BRAF (B-Raf proto-oncogene, serine/threonine kinase)
Diseases named in the same sentence as BRAF in open-access papers (continued):
Sharing a sentence is not in itself a finding about the gene and the disease.
melanoma (continued). "Studies targeting BRAF, NRAS and KIT showed KIT as the most common mutated gene in urogenital tract melanomas, with a mutation frequency higher than 25%." (PMID 33525348, 2021). "In summary, our study demonstrates that the restoration of mTORC1 activity is important in mediating acquired resistance of BRAF-mutant melanoma to MAPK inhibitors." (PMID 34304249, 2021). "Guided by these previous observations and successful clinical translation of drugs targeting epigenetic regulators we performed a chemical genetic screen in BRAF mutant melanoma cells." (PMID 34771678, 2021). "The choice of adjuvant therapy for patients with BRAF mutant stage III melanoma is unclear, with compelling evidence supporting use of either TT or IT." (PMID 33087895, 2021). "Hotspot mutations in BRAF and NRAS define the two major subtypes of melanoma that are mutually exclusive, with 50% of patients harboring BRAFV600E mutations and 30% of patients harboring NRAS hotspot mutations." (PMID 33769711, 2021). "We also showed that RICTOR contributed to melanoma resistance to BRAF inhibitors and rendered the cells very sensitive to mTORC2 inhibition." (PMID 34680615, 2021). "Melanoma is mostly treated with inhibitors of the MAPK signaling pathway that targets BRAF or MEK kinase." (PMID 34079763, 2021). "Herein, we discuss resistance mechanisms in detail and the potential role for RASSF1A reactivation to re-sensitise BRAF mutant melanomas to therapy." (PMID 34066022, 2021). "Vemurafenib (Vem) was the first FDA-approved BRAF inhibitor and gained great clinical success in treating late-stage melanoma." (PMID 33841154, 2021). "A majority of melanoma tumors harbor the activating BRAFV600E mutation and can be treated with BRAF- and MEK-inhibitors at the metastatic stage, resulting in significantly improved survival." (PMID 33947959, 2021). "As reported in patients with BRAF V600E or V600K mutant stage III melanoma treated with 12-months adjuvant dabrafenib + trametinib, RFS is 52% at 5-years of follow-up." (PMID 35008274, 2021). "Treatment with TT was resumed after recovery, however this patient (with a BRAF insertion) eventually died due to melanoma progression." (PMID 34743688, 2021). "For example, in oncogenic BRAF-driven melanomas, BRN2 expression is elevated through hyperactivated MAPK signaling, which transcriptionally represses the cGMP-specific phosphodiesterase PDE5A." (PMID 34604096, 2021). "Frequent alteration of the BRAF gene is observed in 80% of melanoma and about 45% of sporadic papillary thyroid cancers." (PMID 34439194, 2021). "Alternatively, in BRAF inhibitor-resistant human melanoma cell lines, there is pronounced hypomethylation of the EGFR gene promoter, leading to increased expression of EGFR and metastasis through PI3K/Akt signaling." (PMID 34067095, 2021). "Studies in our laboratory have shown encouraging in vivo anti-melanoma activity of palbociclib in combination with BRAF-MEKi." (PMID 34944961, 2021). "Here the authors track the responses of single melanoma cells to BRAF inhibitors and show that a subset of cells rapidly escapes drug via non-genetic mechanisms and incurs DNA damage." (PMID 33741929, 2021). "For example, a study of BRAF inhibition in malignant melanoma found activation of at least 6 signaling pathways." (PMID 34853306, 2021). "In melanoma and other cancers, this pathway is often activated by a mutant form of BRAF, which activates MEK and stimulates tumor cell growth." (PMID 34885115, 2021). "BRAF inhibitor-induced autophagy results in drug resistance and displays poor response to chemotherapeutic agents in melanoma." (PMID 33809137, 2021). "EGFR was furthermore reported to mediate resistance to BRAF inhibitors in melanoma, and the high EGFR expression in colorectal cancer cells is considered to be the reason for the lack of BRAF inhibitor responsiveness of BRAFV600E mutant colorectal cancer." (PMID 33916908, 2021).
melanoma (continued). "More recently, vemurafenib with cobimetinib and encorafenib with binimetinib have also been FDA approved as BRAF/MEK combination therapy for the treatment of melanoma." (PMID 33807778, 2021). "The COLUMBUS study evaluated the role of combination targeted therapy in the treatment of patients with BRAF+ advanced melanoma." (PMID 34064013, 2021). "In this study, we modify Huang and Ferrell’s model to capture cellular signalling dynamics in a specific MAPK pathway: the BRAF-MEK-ERK cascade in BRAFV600E-mutant melanoma." (PMID 34621046, 2021). "Vemurafenib is a selective inhibitor of V600-mutated BRAF, and was the first-in-class mitogen-activated protein (MAP) kinase pathway inhibitor approved for the treatment of melanoma." (PMID 34109122, 2021). "The total number of CTCs in four of five patients with stage IV melanoma fluctuated in response to BRAF/MEK inhibitor treatment, suggesting that CTC number has potential for use as a drug response marker in advanced disease patients." (PMID 33731038, 2021). "Real world data assessing the survival of melanoma patients comparing first- and second-line therapy suggested that, in second-line or higher, BRAF plus MEK inhibition was superior to anti-PD-1 monotherapy throughout the first three years." (PMID 33435389, 2021). "BRAF and MEK inhibitors, Dabrafenib and Trametinib, have been approved for the treatment of BRAF V600E/K-mutant melanoma but only show transient clinical benefit due to the rapid onset of resistance." (PMID 34828352, 2021). "Class I BRAF mutant melanomas also acquire resistance to RAFi via increases in RTK and NRAS expression, which increasing the proportion of active RAF." (PMID 33367512, 2021). "Current therapies for advanced melanoma include several clinically approved BRAF inhibitors (BRAFi; e.g., vemurafenib, dabrafenib) in combination with MEK inhibitors (MEKi; e.g., trametinib)." (PMID 34771678, 2021). "Multigene panel sequencing is routine in many solid tumours but has been relatively limited in melanoma due to the immediate clinical impact of BRAF assessment in directing clinical care." (PMID 34572747, 2021). "The increased ratio of BRAF mutant melanomas in female versus male patients resulted in more targeted therapy initially being prescribed to female patients." (PMID 34572865, 2021). "Overall, 116 patients (42.2%) were diagnosed with BRAF-mutant melanoma, while 114 patients received at least one line of systemic therapy before initial ICI administration." (PMID 34680252, 2021). "Targeted therapy was more commonly chosen over immunotherapy as a second line treatment in BRAF mutant melanoma." (PMID 34109763, 2021). "Pharmacological inhibition of ASAH1 also attenuated melanoma growth and enhanced the effectiveness of BRAF kinase inhibitor in the cell cultures and mice." (PMID 33766731, 2021). "Following the BRIM trial, several BRAF inhibitors emerged as effective treatment options in BRAFV600E/K mutant melanomas." (PMID 34831002, 2021). "The cBio Cancer Genomics Portal (cBioPortal) is one of the most comprehensive public databases and allowed us to analyze the BRAF, KRAS, and KIT mutation status from 14 different studies focused on melanomas." (PMID 34769348, 2021). "Although BRAF inhibitors have been utilized for melanoma therapy, advanced melanoma patients still face a low five‐year survival rate." (PMID 33377602, 2021). "In this study, we have systematically studied mTORC1 signaling in different subsets of established BRAF-mutant melanoma cells that acquired resistance to combined BRAF and MEK inhibition." (PMID 34304249, 2021). "Among all kinases, BRAF fusions are the most commonly observed across several tumor types, including prostate cancer, melanoma, radiation-induced thyroid cancer, and pediatric low-grade gliomas." (PMID 33716974, 2021). "In some cases, BRAF-mutant melanoma patients after a first line of treatment with targeted therapy receive subsequent treatment with ICIs." (PMID 33917181, 2021).
melanoma (continued). "The mutant of BRAF in melanoma patients has predicted a good survival and the NRAS or NF1-mutant subtype of melanoma was associated with poor outcomes." (PMID 34745259, 2021). "We demonstrated that the combination of ECCA with a BRAF inhibitor strongly enhanced the growth inhibition of melanoma cells." (PMID 34103468, 2021). "The next clinical trial, titled “Use of Exome Sequence Analysis and Circulating Tumour in Assessing Tumour Heterogeneity in BRAF Mutant Melanoma”, concerns the evolution of BRAF melanoma in response to vemurafenib or dabrafenib." (PMID 34575876, 2021). "With respect to melanoma, BRAF alteration was the main driver, with comparable SNV and CNV frequencies (52.63% and 10.53% in our cohort, 51.40% and 6.80% in TCGA respectively)." (PMID 33947144, 2021). "In melanoma, ERK activity stimulated by BRAF is associated with MITF ubiquitin-dependent degradation." (PMID 34571969, 2021). "First, the high alternations level on chromosome 7 hot zones are in accordance with the overexpression of nearby EGFR, MET, and BRAF genes in glioma, lung cancers, and melanoma." (PMID 34054918, 2021). "The CheckMate 066 trial investigated nivolumab monotherapy as first-line treatment for patients with previously untreated BRAF wild-type advanced melanoma." (PMID 34447613, 2021). "It has been estimated that increased BRAF copy number is present in 20% of cases of acquired resistance to BRAFi therapy in melanoma." (PMID 33807778, 2021). "We later showed that BRAF inhibitor‐resistant melanoma cells have increased reactive oxygen species (ROS) levels due to overactivation in MAPK signaling." (PMID 33955157, 2021). "BRAF inhibition can accelerate the growth of cutaneous squamous cell carcinomas and melanoma resulting from the activation of MAPK signaling." (PMID 33216198, 2021). "It has recently been shown that autophagy, a conserved cellular recycling process, is increased in BRAF-driven melanoma upon inhibition of BRAFV600E signaling." (PMID 34298710, 2021). "In this study, we analyzed the prognostic role of NRAS, KIT, BRAF, IGF2R and SF3B1 mutations in a series of mucosal melanomas." (PMID 34571863, 2021). "In this study, our retrospective analysis found that the time of TBIL, DBIL, or IBIL below the threshold levels was positively correlated with the clinical outcome of patients with BRAF mutant melanoma who received only vemurafenib therapy." (PMID 34222023, 2021). "The GPA is calculated by adding the score values for the three parameters for age, KPS, extracranial metastases, and the number of brain metastases; the melanoma molGPA by also adding the value of the BRAF status." (PMID 33993415, 2021). "Although the mechanism is not elucidated in GC, loss of NF1 has been associated with resistance to EGFR TKIs in lung adenocarcinomas and resistance to BRAF inhibitor in melanoma by increasing MAPK and/or PI3K signaling via negatively regulating Ras." (PMID 34399705, 2021). "BRAF mutant melanoma is often more clinically aggressive and occurs in younger patients, therefore early identification is essential for optimal disease management." (PMID 34066966, 2021). "Mutations of BRAF are detected in several solid cancers, such as NSCLC, melanoma, and colorectal cancers." (PMID 34276690, 2021). "BRAF inhibition as well as knockdown of BRAFV600E in multiple patient-derived melanoma cell lines blocked IL-1α production." (PMID 33746966, 2021).
melanoma (continued). "To approach this issue, we performed a retrospective study that involved 382 patients with advanced BRAF V600 mutant melanoma, who received TT in twelve medical centers." (PMID 34064013, 2021). "Combined BRAF/MEK small molecule inhibition is an established therapy for BRAFV600E-mutant melanoma." (PMID 33275172, 2021). "For example, BRAFV600E, a constitutively active form of the BRAF serine/threonine kinase, drives melanoma and has been shown to promote IL-6, IL-10, and VEGF secretion in a STAT3 dependent manner." (PMID 33807608, 2021). "Regardless, our study suggests that there is a significant incidence of intracranial disease burden from melanoma even in the setting of controlled or improving extracranial disease in patients while on BRAF/MEK targeted therapy and immunotherapies." (PMID 33824801, 2021). "Autophagy was initially demonstrated to be a resistance mechanism to BRAF V600E mutant melanoma and brain cancer." (PMID 34830283, 2021). "In BRAF-mutant melanomas, comparable states tolerant of MAPK inhibition have been associated with variations in differentiation state." (PMID 33750776, 2021). "The MEK (mitogen-acitvated protein kinase kinase) and BRAF (serine/threonine-protein kinase B-Raf coding gene) inhibitor combination therapy is currently part of the standard of care for stage IIIC/IV of BRAF mutant melanoma." (PMID 32248296, 2021). "The present study demonstrated a role for PYK2 in melanoma progression, and provided a potential combination-therapy strategy to improve the therapeutic efficiency of BRAF inhibitors in melanoma patients." (PMID 34570440, 2021). "The FDA and the European Medicines Agency (EMA) approved three BRAF and MEK inhibitor combination TTs for patients with unresectable/metastatic BRAF mutated melanoma: dabrafenib plus trametinib, vemurafenib plus cobimetinib and encorafenib plus binimetinib." (PMID 33801689, 2021). "In the COLUMBUS trial, the median overall survival of patients with BRAF V600-mutant melanoma was 33.6 months with COMBO450 (encorafenib plus binimetinib), 23.5 months with ENCO300 (encorafenib), and 16.9 months with VEM (vemurafenib)." (PMID 34804979, 2021). "We also provide a comprehensive review of promising individualized novel treatment approaches in non-BRAF mutant melanoma." (PMID 34831002, 2021). "BRAF mutations and TERT promoter mutations have synergies in the diagnosis of thyroid cancer, and we have also found synergies between BRAF mutations and TERT promoter mutations in patients with melanomas, epithelial glioblastomas and gliomas." (PMID 34923978, 2021). "They concluded that, among melanoma patients with an earlier stage tumor, beside SLN negativity, intensive surveillance is required, taking into account BRAF and NRAS mutation status." (PMID 34209415, 2021). "Metformin treatment of BRAF-mutant melanoma cells was found to upregulate VEGF expression in an AMPK- dependent manner." (PMID 35052372, 2021). "In melanoma, the BRAF (V600E)/ERK1/2 pathway is especially involved in regulating the expression and/or activity of MITF, suggesting the role of MITF as a melanoma addiction oncogene." (PMID 34722301, 2021). "BRAF mutations are observed in 36 to 83% of cases of PTC in all age groups and in 63% of melanoma cases." (PMID 33578751, 2021). "Drug-induced sarcoidosis has been reported secondary to modern melanoma therapies including immune-checkpoint inhibitors and first generation BRAF inhibitors such as vemurafenib and dabrafenib." (PMID 35663773, 2021). "Further research should investigate if ABC transporters act as additional targets of miR-129-5p in the context of BRAF/MEK inhibitor resistance in melanoma." (PMID 34063443, 2021). "The MAPK pathway is constitutively active in a large percentage of melanomas because of activating NRAS and BRAF mutations or inactivating NF1 mutations." (PMID 33766731, 2021).
melanoma (continued). "A high frequency of BRAF alterations besides the thyroid cancers occurs in the “Melanoma TCGA-cancer” cohort (54% of 444 cases)." (PMID 34630336, 2021). "The inhibition of either BRAF or MEK in melanoma patients is assumed to result in an enhanced tumor antigen expression or the release of these antigens caused by cell death, which is then followed by an increased T-cell infiltration." (PMID 33275172, 2021). "Melanoma cells under BRAF inhibitor treatment developed signatures of neural crest stem cells and epithelial-to-mesenchymal transition, expressing genes associated with elevated invasiveness and migration." (PMID 34591417, 2021). "Genetic inactivation of several identified fitness genes had an effect on melanoma cell proliferation similar in size to BRAF inactivation." (PMID 32767816, 2021). "Normally, melanoma cells with activation of the BRAF/MAPK pathway (M14, MALME-3M, UACC-62, UACC257) presented suppressed levels of MITF and PGC-1α—the master regulator of the mitochondrial biogenesis and OXPHOS." (PMID 33730175, 2021). "We demonstrate the utility of this approach in BRAF-mutant melanomas by using JIB-04 and SP2509, as investigational tools, to block epigenetically diverse populations of MAPK inhibitor-tolerant cells." (PMID 33750776, 2021). "Taken together, our data suggest that proper trafficking of PMCA4b was crucial for determining the shape and migratory behavior of these BRAF mutant melanoma cells." (PMID 33802790, 2021). "The acquisition of resistance, particularly to BRAF inhibitors such as vemurafenib, remains one of the most reported drawbacks in melanoma targeted therapy." (PMID 33916029, 2021). "The introduction of BRAF/MEK-directed targeted therapy (TT) has significantly improved the management of patients with advanced BRAF-V600-mutant melanoma." (PMID 34065877, 2021). "A functional genomics study conducted using genome-scale open reading frame (ORF) resistance screens revealed a cyclic AMP-dependent melanocytic signaling network as another possible contributor to BRAF/MEK inhibitor resistance in melanoma." (PMID 33807778, 2021). "This prompted us to examine its antiproliferative properties in combination with other inhibitors in melanoma BRAF (V600E) cells." (PMID 33672955, 2021). "Nowadays, some targeted therapeutic strategies, including BRAF and MEK inhibitors, have enhanced survival benefits for melanoma patients, but treatment failure caused by drug resistance remains an obstacle 6-10." (PMID 33531976, 2021). "BRAF V600E mutations are the most frequent and earliest events that occur on low-CSD melanoma and associated nevi." (PMID 34440462, 2021). "Taking advantage of an array of CR cell lines and xenografts, we now present evidence for a crucial role of mTORC1 in BRAF-mutant CR melanoma." (PMID 34304249, 2021). "Approximately 90% of melanoma exhibit some cell cycle pathway dysregulation which provides a strong rationale to combine CDK4/6i with BRAF-MEKi." (PMID 34944961, 2021). "On the other hand, BRAF-i can increase melanoma antigen presentation and T cell infiltration and reduce immunosuppressive cytokines." (PMID 35008245, 2021). "In melanoma, inhibitors of the common driver mutations MEK and BRAF are now frequently used in combination with ICB." (PMID 35082797, 2021). "During the last decade, BRAF-mutant melanomas have become amenable to new targeted therapies based on initially BRAF inhibitor (BRAFi) and now on its combination with a MEK inhibitor (MEKi)." (PMID 34063443, 2021). "In contrast to melanomas, BRAF-driven colorectal cancers require EGFR inhibition to prevent an activation of the compensatory signaling cascade, and are usually treated by combined administration of anti-EGFR antibodies and antagonists of mutated BRAF." (PMID 34681592, 2021). "A prospective, single-arm, phase II study of axitinib with carboplatin and paclitaxel showed a safe profile and favored disease control in advanced BRAF wild-type melanoma." (PMID 33918490, 2021).